PINK1 (PTEN induced kinase 1)
Diseases named in the same sentence as PINK1 in open-access papers (continued):
Sharing a sentence is not in itself a finding about the gene and the disease.
amyotrophic lateral sclerosis (18 papers, 2016 to 2025). Amyotrophic lateral sclerosis (ALS) is a neurodegenerative disease characterized by progressive muscular paralysis reflecting degeneration of motor neurons in the primary motor cortex, corticospinal tracts, brainstem and spinal cord. "Independently from the direct effects of ROS in mitophagy, autosomal recessive forms of glaucoma, familial Parkinson's disease, and amyotrophic lateral sclerosis (ALS) have been associated with dysfunctions of PINK1-Parkin pathway." (PMID 33953963, 2021). "Mutations in VCP contribute to FTD, amyotrophic lateral sclerosis, inclusion body myositis and Paget’s disease; mutations in PINK1 elicit motor and cognitive dysfunction characteristic of early-onset PD/PDD." (PMID 30783609, 2018). "Furthermore, dysregulation of PINK1/PARKIN signalling has been associated with amyotrophic lateral sclerosis (ALS) and Huntington’s disease (HD), as well as eye diseases, such as age-related macular degeneration (AMD), and is associated with retinal degeneration." (PMID 33168089, 2020). "In amyotrophic lateral sclerosis (ALS), disrupted PINK1/Parkin signaling is associated with SOD1 and TDP-43 pathology." (PMID 40750884, 2025). "However, downregulating expression of either PINK1 or Parkin genes ameliorated neurodegeneration phenotypes in amyotrophic lateral sclerosis (ALS)." (PMID 35126814, 2022). "Parkin and PINK1 play an important role in mitochondrial quality control, whose malfunction may also be involved in the pathogenesis of amyotrophic lateral sclerosis (ALS)." (PMID 30237395, 2018). "This study identifies isoginkgetin (ISO) as a potent inducer of PINK1-Parkin-dependent mitophagy that improves mitochondrial function and alleviates amyotrophic lateral sclerosis (ALS) pathology in animal and patient-derived models." (PMID 41094045, 2025). "The PINK1-Parkin axis is related to exercise-induced mitochondrial degeneration, and in patients with sporadic amyotrophic lateral sclerosis (ALS), the expression of PINK1 is significantly reduced." (PMID 34751247, 2021). "OPTN, a causative gene of mitochondrial dysfunction-related amyotrophic lateral sclerosis (ALS) and glaucoma diseases, was shown to participate in PINK1/Parkin-mediated mitophagy by recruiting damaged mitochondria via its LIR." (PMID 32235615, 2020). "These disorders include, among others, Parkinson's disease (PD) with SNCA, PINK1, PARK2, GBA1, and LRRK2 mutations, amyotrophic lateral sclerosis (ALS) with TDP43 mutation, Huntington's disease (HD) with HTT mutation, and Spinal muscular atrophy (SMA) with SMN1 mutation." (PMID 27313629, 2016).
colon carcinoma (18 papers, 2020 to 2025). "Herein, we revealed for the first time that the inhibition of HSP90 in colon cancer cells was associated with the downregulation in PINK1, thus terminating its protective roles." (PMID 39921807, 2025). "Moreover, we substantiate the requirement of PINK1 for optimal growth of Ras-transformed cells by showing that human HCT116 colon carcinoma cells (carrying an endogenous RasG13D mutation) with CRISPR/Cas9-introduced PINK1 gene deletions also show reduced mitochondrial fission and decreased growth." (PMID 35600352, 2022). "Aloe vera gel glucomannan induces colon cancer cell death via the PINK1/Parkin mitophagy pathway driven by mitochondrial damage." (PMID 40316942, 2025). "Downregulating PINK1 ensued after inhibiting HSP90 incited intense oxidative stress in colon cancer cells." (PMID 39921807, 2025). "Targeting HSP90 in colon cancer cells disrupts their survival by decreasing PINK1 and increasing BNIP3, which activates oxidative and endoplasmic reticulum stress, ultimately triggering apoptosis." (PMID 39921807, 2025). "Subsequently, PINK1 was reported to be high expression in mouse cancer cells of melanoma and colon carcinoma, which displayed significant metastatic potential." (PMID 37940999, 2023). "In the study, we found that the number of autolysosomes was decreased and the expression of PINK1 and Parkin proteins was decreased in colon cancer cells after Plasmodium infection." (PMID 35668501, 2022). "The comprehension of PINK1/Parkin-related mitophagy signaling in colon cancer is of emerging interest." (PMID 34360883, 2021). "Furthermore, we examined the change in endogenous PINK1 levels in the human colon cancer HCT116 cell line with FBW7 deletion." (PMID 38508312, 2024). "In addition, Plasmodium infection disturbed mitochondrial biogenesis and mitophagy through the reduced expression of PGC-1α, PINK1, and Parkin proteins in colon cancer cells." (PMID 35668501, 2022). "Increases in both PINK1 and LC3BII levels were observed in both osteosarcoma and colon carcinoma control cells." (PMID 37834071, 2023). "Conversely, the level of PINK1 was found to be significantly reduced (approximately 35%) or nearly unchanged in IF1-silenced cells derived from osteosarcoma and colon carcinoma, respectively." (PMID 37834071, 2023). "The activation of the PINK1/Parkin-mediated mitophagy by aloe gel glucomannan (AGP), significantly induces the cell death of colon cancer cells through the accumulation of impaired and ROS-generating mitochondria." (PMID 36766737, 2023). "Together, these findings support a critical role of PINK1/Parkin-mediated mitophagy in mitochondrial dysfunction and apoptosis induced by δVB in SW480 and SW620 colon cancer cells." (PMID 34360883, 2021). "We reported for the first time that HSP90 inhibition intensely increased oxidative stress and endoplasmic reticulum stress through downregulating PINK1 and upregulating BNIP3 in colon cancer cells, subsequently reduced colon cancer cells survival and increased its apoptosis." (PMID 39921807, 2025). "Transmission electron microscopy (TEM) was used to observe the ultrastructural change in colon cancer cells, and the expression of mitochondrial biogenesis correlative central protein, PGC-1α, and mitophagy relevant crucial proteins, PINK1/Parkin, were detected by western blot." (PMID 35668501, 2022).
ischemia (17 papers, 2013 to 2025). A hypoperfusion of the BLOOD through an organ or tissue caused by a PATHOLOGIC CONSTRICTION or obstruction of its BLOOD VESSELS, or an absence of BLOOD CIRCULATION. "Either PINK1 or Parkin KD impaired +dP/dt and −dP/dt at 60, 90, and 120 minutes following 60 minutes of global ischemia, suggesting that the PINK1/Parkin pathway contributes to myocardial IRI." (PMID 41446187, 2025). "The results showed that compared with the sham group, the level of PINK1 was significantly decreased in ischemia and reperfusion group, and the decrease in reperfusion group was more significant than that in ischemic group." (PMID 35586047, 2022). "Here, using pharmacological and genetic approaches, we provide evidence that activation of RhoA stabilizes PINK1 protein at mitochondria, induces mitophagy, and promotes cardiomyocyte survival against ischemia both in vitro and in vivo." (PMID 35760846, 2022). "Consistent with previous reports, mitochondrial PINK1 levels were increased by ischemia in AAV9-GFP mice; notably this was further increased by expression of AAV9-RhoA." (PMID 35760846, 2022). "Melatonin prevents the opening of the mitochondrial permeability transition pore (mPTP) and inhibits the PINK1/Parkin activation within the microcirculating endothelial cells of an ischemia/reperfusion mouse model." (PMID 33669743, 2021). "Hearts excised from PINK1+/+, PINK1+/− and PINK1−/− mice were subjected to 35 minutes regional ischemia followed by 30 minutes reperfusion." (PMID 23638067, 2013). "Shan and co-workers have reported that PINK1 can protect neonatal rat cortical neurons against simulated ischemia." (PMID 23638067, 2013). "Similar to the PINK1/Parkin pathway, BNIP3, as a member of the Bcl-2 family, also induces mitophagy in response to ischemia-related stress and participates in the pathological and protective processes of IRI." (PMID 41451126, 2025). "Some studies have found that the PINK1/PARKIN-mediated mitophagy pathway is activated after CI, and mitochondrial division inhibitors aggravate ischemia-induced nerve cell damage, suggesting that promoting mitophagy has a protective role in CI injury." (PMID 37234709, 2023). "Omentin1 maintained mitochondrial dynamical homeostasis and promoted PINK1/Parkin-dependent mitophagy via SIRT3/FOXO3a signaling, thereby improving MI-induced HF and enhancing the resistance of myocardium to prolonged ischemia injury." (PMID 36192726, 2022). "Intriguingly, a previous study showed that HK2 separation from mitochondria triggered Parkin‐mediated mitophagy that was independent of PINK1 pathway in response to ischemia." (PMID 36514923, 2023). "However, compared with siRNA-negative control (si-NC), si-PINK1 abolished HPC-induced neuroprotection as evidenced by a dramatic decrease in surviving and NeuN-positive cells after ischemia." (PMID 34145219, 2021). "Activation of ALDH2 inhibits phosphatase and PINK1/Parkin expression both in ischemia/reperfusion rats and hypoxia/reoxygenation H9C2 cells, protecting the heart against ischemia/reperfusion injury via regulating mitophagy, preventing 4-hydroxynonenal, ROS, and mitochondrial superoxide accumulation." (PMID 33669743, 2021).
liver fibrosis (16 papers, 2020 to 2025). "PM2.5 may activate PINK1/Parking pathway signal and induce mitochondrial autophagy by increasing ROS, and further activate HSCs (hepatic stellate cells) to cause liver fibrosis." (PMID 36699051, 2022). "Lipotoxic hepatocyte-derived LIMA1-enriched sEVs play a crucial role in promoting HSCs activation in NAFLD-related liver fibrosis by negatively regulating PINK1 mediated mitophagy." (PMID 38822260, 2024). "For example, PM2.5 induced mitochondrial oxidative stress damage in hepatic stellate cells through the PINK1/Parking pathway, which led to cellular autophagy and liver fibrosis." (PMID 37737576, 2023). "In this study, we found that PINK1/parkin-mediated mitophagy was downregulated during the activation of HSCs and development of hepatic fibrosis, while MitoQ enhanced mitophagy and reduced ROS levels in the HSCs and reduced liver fibrosis." (PMID 34825063, 2021). "Our results showed that MitoQ inhibited the activation of HSCs and alleviated hepatic fibrosis by enhancing PINK1/parkin-mediated mitophagy." (PMID 34825063, 2021). "There are scarce data on MitoQ and PINK1/parkin-mediated mitophagy in the process of liver fibrosis." (PMID 34825063, 2021). "Namely, PINK1/parkin-mediated mitophagy is enhanced in HSCs in a hepatic fibrosis-reversal model, and the inhibition of mitophagy enhances the activation of HSCs in mice." (PMID 34825063, 2021). "PA treatment also alters the miRNA expression profiles in hepatocyte-derived exosomes, which promotes HSCs activation by targeting PPAR-γ expression or Phosphatase and Tensin homolog (PTEN)-induced Kinase 1 (PINK1), thereby accelerating liver fibrosis progression." (PMID 40129979, 2025). "Moreover, PM2.5 has been found to promote the activation of HSC and the development of hepatic fibrosis by activating PINK1/Parkin-mediated mitophagy." (PMID 39183973, 2024). "Studies have shown that inactivation of Nrf2, either through direct knockdown in CKD or indirect knockdown of endothelial nitric oxide synthase (eNOS) in hepatocytes, exacerbated OS and impaired PINK1/Parkin-mediated mitophagy, contributing to the progression of renal and hepatic fibrosis." (PMID 39183973, 2024). "Thus, we speculated that MitoQ enhanced PINK1/parkin-induced mitophagy in HSCs to reduce liver fibrosis." (PMID 34825063, 2021). "We previously elucidated that inhibition of Pink1-mediated mitophagy would enhance HSC activation and accelerate liver fibrosis in NASH." (PMID 38461242, 2024). "Moreover, inhibition of Akt1-mediated ROS production in Kupffer cells blocked PINK1/Parkin-mediated mitophagy activation, contributing to the regression of carbon tetrachloride (CCL4)-induced hepatic fibrosis." (PMID 39183973, 2024). "Particulate matter (PM)-induced excess ROS activated PINK1/Parkin-mediated mitophagy, promoting hepatic fibrosis, thereby demonstrating the negative role of mitophagy." (PMID 39183973, 2024). "We did not observe consistent changes in PINK1, another critical protein for mitophagy, in two liver fibrosis-induced samples." (PMID 37834275, 2023). "Melatonin could upregulate mitophagy, and reduce mitochondrial DNA damage and mitochondrial dysfunction by increasing PINK1 and PARKIN expression, thus alleviating liver fibrosis in rats." (PMID 37629033, 2023). "However, TIM‐4 interference in the KCs inhibited Akt1‐mediated ROS production, resulting in the suppression of PINK1, Parkin and LC3‐II/I activation and the reduction of TGF‐β1 secretion during liver fibrosis." (PMID 31755616, 2020).
dementia (15 papers, 2011 to 2025). Loss of intellectual abilities interfering with an individual's social and occupational functions. "Additionally, APP haploinsufficiency prevented memory deficits in familial British dementia mouse models, and PTEN-induced putative kinase 1 (PINK1) was associated with memory impairment induced by APP." (PMID 38396891, 2024). "Our findings indicated a significantly lower CSF PINK1 and ULK1 levels in FTLD compared to AD, with FTLD dementia showing particularly low CSF PINK1 levels compared to AD-dementia." (PMID 39972393, 2025). "Meanwhile, a high ATF4 and PINK1 concentrations were observed in serious memory status in terms of clinical dementia rating (CDR) scores." (PMID 39394148, 2024). "Several intensively studied dementia-affiliated genes such as APOE (apolipoprotein E), GBA1 (glucosylceramidase beta 1), LRRK2 (leucine rich repeat kinase 2), and PINK1 (PTEN induced kinase 1) encode proteins that function in the human metabolism." (PMID 36771351, 2023). "PINK1 and Parkin mRNA levels were downregulated in the hippocampi of SAMP8 mice with dementia but were highly upregulated in PNS-treated mice." (PMID 38575939, 2024). "Moreover, our results on the absence of dementia are compatible with literature concerning PRKN and PINK1 mutations although there are some exceptions notably for PINK1 carriers." (PMID 39195564, 2024). "In other forms, such as those caused by recessive mutations in the parkin (PARK2), PINK1 (PARK6), DJ-1 (PARK7), and ATP13A2 (PARK9), the phenotype is more often atypical due to younger-onset, presence of additional clinical signs (dementia, pyramidal signs), or absence of Lewy body-pathology." (PMID 21347293, 2011). "Notably, dementia is not typical of PINK1 patients even after a long disease duration although cognitive deficits may occur in some patients." (PMID 39195564, 2024).
renal fibrosis (15 papers, 2020 to 2025). A final common manifestation of a wide variety of chronic kidney diseases characterized by glomerulosclerosis and tubulointerstitial fibrosis. "In addition, Sirt1 is involved in activating PTEN-induced kinase 1 (PINK1)/Parkin-associated mitochondrial autophagy and is an effective therapeutic strategy for preventing renal fibrosis." (PMID 38347622, 2024). "Taken together, PINK1-Parkin-mediated mitophagy ameliorated renal fibrosis and alleviated the development of hyperuricemia -induced CKD by reducing mtROS and NLRP3 mediated inflammation." (PMID 38680884, 2024). "Quercetin has been reported to reduce RTECs senescence and alleviate renal fibrosis by activating Sirt1/PINK1/Parkin-mediated mitochondrial phagocytosis." (PMID 38347622, 2024). "In CKD patients and experimental kidney disease, mitophagy-related genes such as PINK1 and Parkin are downregulated, and Pink1 and Parkin deletion blocks mitophagy, alters mitochondrial homeostasis, and increases renal fibrosis." (PMID 37175915, 2023). "As reported, mitophagy-related genes PINK1, Mfn2 and Parkin were decreased in human patients and animal models with renal fibrosis." (PMID 36353377, 2022). "Quercetin at 20 μM improves renal tubular epithelial cell senescence induced by angiotensin II and slowed down renal fibrosis progression by activating Sirt1/PINK1/Parkin pathway." (PMID 34175838, 2021). "The PINK1 / Parkin signaling pathway can affect renal fibrosis by influencing mitophagy." (PMID 40225869, 2025). "Pink1−/− and Parkin−/− mice exhibited suppression of mitophagy, impaired mitochondrial homeostasis, enhanced recruitment of profibrotic M2 macrophages, and aggravated renal fibrosis." (PMID 36353377, 2022). "For example, quercetin, a dietary flavonoid, can reduce RTEC senescence in renal fibrosis via SIRT1/PINK1/mitophagy axis, while liraglutide, a glucagon-like peptide-1 receptor agonist, can improve mitochondrial homeostasis in heart injury through the identical signaling axis." (PMID 34359852, 2021). "Furthermore, genetic deletion of Nrf2 reduced PINK1/Parkin-mediated mitophagy activation and led to increased renal tubular necrosis and renal fibrosis." (PMID 34858188, 2021). "For instance, Mdivi-1, a mitochondrial inhibitor, can reduce the expression levels of PINK1, PARK2, and LC3II, activate the TGF-β1 signaling pathway in HK-2 cells under hypoxic conditions, thereby exacerbating renal fibrosis." (PMID 40305351, 2025). "In conclusion, UPS is mainly involved in renal fibrosis through TGF-β, Wnt / β - catenin, and PINK1 / Parkin pathway and factors such as EGFR and CHK1." (PMID 40225869, 2025). "A previous study showed that the PINK1 gene deletion markedly increased the transforming growth factor beta 1 (TGF‐β1) expression in renal tubular cells, and renal fibrosis." (PMID 37183600, 2023). "Notably, the PINK1 pathway and SIRT1-PINK1 axis have been identified as potential therapeutic targets for renal fibrosis by restoring mitochondrial homeostasis." (PMID 40702453, 2025). "In this study, we showed that VDR could ameliorate renal fibrosis in STZ-induced diabetic mice by up-regulating the expression of BNIP3 and PINK1." (PMID 38697845, 2024). "In the present study, we also confirmed increased renal fibrosis and tubular injury in PINK1 knockout mice, and the more noticeable aging phenomenon was more prominent in PINK1 knockout mice." (PMID 37183600, 2023). "PINK1 and Parkin knockout mice shows more severe renal dysfunction in the nephrotoxin-induced CKD model and the unilateral ureteral obstruction (UUO) model of renal fibrosis." (PMID 34359852, 2021).